CLEC17A (C-type lectin domain containing 17A)
Description:
Cell surface receptor which may be involved in carbohydrate-mediated communication between cells in the germinal center. Binds glycans with terminal alpha-linked mannose or fucose residues.
Synonyms: FLJ45910
Tractability: Antibody: UniProt predicts a signal peptide or a membrane-spanning region.
Gene: Protein-coding gene on chromosome 19 (14,583,084 to 14,612,035, forward strand). Ensembl gene ENSG00000187912.
Subcellular location: Membrane
Gene Ontology:
Molecular function: D-mannose binding; fucose binding; identical protein binding; protein binding; pattern recognition receptor activity
Biological process: immune response
Cellular component: cell surface; external side of plasma membrane; membrane
Genetic constraint (gnomAD): Loss-of-function variants: 33 observed, 56.87 expected, observed/expected ratio (o/e) 0.58, 90% interval 0.44 to 0.78. The upper end of that interval is the gene's LOEUF score, 0.78, which puts it in group 3 of 6, group 1 being the genes least tolerant of losing a copy. Missense variants: 378 observed, 439.5 expected, observed/expected ratio (o/e) 0.86, 90% interval 0.79 to 0.94. Synonymous variants: 149 observed, 150.87 expected, observed/expected ratio (o/e) 0.99, 90% interval 0.86 to 1.13.
Homologues: Orthologues: chimpanzee CLEC17A (98% identical), macaque CLEC17A (85% identical), dog CLEC17A (62% identical), pig CLEC17A (62% identical), Drosophila melanogaster tfc (14% identical), Caenorhabditis elegans clec-266 (11% identical), Drosophila melanogaster CG14866 (11% identical), Caenorhabditis elegans clec-87 (10% identical), Caenorhabditis elegans clec-88 (10% identical), Caenorhabditis elegans clec-91 (10% identical), Drosophila melanogaster lectin-33A (8% identical), Drosophila melanogaster CG34033 (7% identical), and 2 more. Paralogues in human: CLEC10A (19% identical), CD209 (19% identical), ASGR1 (18% identical), CLEC4M (17% identical), CLEC4E (17% identical), CLEC4G (17% identical), CD207 (16% identical), ASGR2 (16% identical), FCER2 (15% identical), CLEC4F (14% identical), CLEC4C (14% identical), CLEC4D (14% identical), and 2 more.
Diseases named in the same sentence as CLEC17A in open-access papers:
CLEC17A is named in the same sentence as 7 diseases in open-access papers, as found by Europe PMC text mining. Sharing a sentence is not in itself a finding about the gene and the disease. The quoted sentences say what the papers report.
lung adenocarcinoma (2 papers, 2020). A carcinoma that arises from the lung and is characterized by the presence of malignant glandular epithelial cells. "The present results further indicate that CLEC17A is associated with immune cell infiltration in lung adenocarcinoma, concurrent with previous reports." (PMID 33072571, 2020). "Finally, hub IRGs CLEC17A, INHA, and XIRP1 were considered novel prognostic biomarkers for lung adenocarcinoma." (PMID 33072571, 2020).
chronic lymphocytic leukemia (1 paper, 2020). "Previous studies have shown that CLEC17A is related to the B cell receptor signaling pathway and plays an important role in the pathogenesis of chronic lymphocytic leukemia." (PMID 33072571, 2020).
melanoma (1 paper, 2023). A malignant, usually aggressive tumor composed of atypical, neoplastic melanocytes. "Moreover, melanoma secretome induces expression of a set of transcripts encoding for protein with tumor-promoting functions including CLEC17A, FR2, SMOX, TOX and ENPP1." (PMID 38239354, 2023).
tumor (4 papers, 2020 to 2024). "CLEC17A may function as a colonization factor in tumor cells, facilitating invasion into the lymph nodes and exhibiting fucosylated motifs that are commonly linked to the epithelial phenotype." (PMID 39679172, 2024).
CLEC17A also shares sentences with these, for which no sentence is quoted: carcinoma (1 paper); lung carcinoma (1); mammary cancer (1).